NANOG (Nanog homeobox)
Diseases named in the same sentence as NANOG in open-access papers (continued):
Sharing a sentence is not in itself a finding about the gene and the disease.
endometrial cancer (6 papers, 2017 to 2024). Primary or metastatic malignant neoplasm involving the endometrium (mucous membrane that lines the endometrial cavity). "The increased expression of CSC-related markers, including CD44, CD133, ALDH1A1, and NANOG, in spheroid cells of endometrial cancer translates into enhanced tumorigenicity." (PMID 38539419, 2024). "Our study revealed that NANOG was expressed in 88.37% of endometrial carcinoma cases; this expression was higher than that in the normal and hyperplastic groups (15% and 60%, respectively)." (PMID 35186145, 2022). "The cancer stem cell markers NANOG and CD 133 are expressed in a high percentage in endometrial carcinoma compared to normal and hyperplasia and their expression is positively correlated with the aggressive behavior of the tumor." (PMID 35186145, 2022). "NANOG expression was detected in 88.37% of endometrial carcinoma cases compared to 15% of the normal proliferative endometrium and 60% of hyperplasia cases." (PMID 35186145, 2022). "We investigated two CSC markers (NANOG and CD 133) in normal, hyperplastic endometrium and endometrial carcinoma." (PMID 35186145, 2022). "NANOG expression was detected in 38 out of 43 (88.37) endometrial carcinoma cases." (PMID 35186145, 2022). "Linc-ROR/miRNA axis-mediated SOX9 activation might not be the only mechanism for regulating cancer stemness in ESCC, given that miR-145 has also been reported to enhance aggressive phenotypes by targeting NANOG in pancreatic and endometrial cancer." (PMID 29237490, 2017). "This implies that NANOG affects endometrial carcinoma oncogenesis, especially well-differentiated in its early stages, and their overexpression may facilitate earlier diagnosis of endometrial carcinoma." (PMID 35186145, 2022). "We used Western blotting to detect the downregulated expression of WTAP in endometrial cancer stem cells compared to that in Ishikawa cells, while other stem cell indicators, such as CD44, CD133, SOX2 and NANOG, were upregulated in ECSCs." (PMID 39044249, 2024). "Correlation of clinicopathological parameters with NANOG and CD133 expression in 43 endometrial carcinoma cases." (PMID 35186145, 2022). "The present work examined the expression of two CSC markers, NANOG and CD133, in 43 endometrial carcinoma cases and compared them to 20 normal and 30 hyperplastic conditions." (PMID 35186145, 2022). "To examine the potential of SOX2, OCT4, NANOG, and MYC as prognostic markers in endometrial carcinoma, we correlated their expression with survival outcomes in patients." (PMID 30510261, 2018). "Endometrial CSCs isolated from endometrial cancer expressing stemness markers, including SOX2, OCT4, MYC, ABCG2, NES, and NANOG, have been demonstrated to show greater expansion potential and colony-forming capabilities, as well as to express self-renewal genes." (PMID 38539419, 2024). "Furthermore, SMOC2 silencing resulted in the diminished clonogenic potential of endometrial cancer and reduced the expression of stemness-related genes, including SOX2, OCT4, and NANOG." (PMID 38539419, 2024). "In contrast, expression of SOX2 and NANOG was significantly lower in CD133+ve cells compared with CD133-ve cells, consistent with earlier findings that ALDH activity may be a better marker of endometrial cancer stem cell activity." (PMID 31083574, 2019).
metastatic tumors (6 papers, 2014 to 2025). "NANOG expression has been associated with cancer cell invasiveness and metastatic tumor presentation." (PMID 25502816, 2014). "NANOG is downregulated during cellular differentiation but is re-expressed in many cancer cells, with higher levels observed in more aggressive and metastatic tumors." (PMID 39451527, 2024). "Firstly, we performed the TF enrichment analysis between primary tumors and metastatic tumors, and finally, seven TFs were identified as differentially expressed TFs, including CBX2, CDX2, FOXA2, KLF4, NANOG, NCAPG, and TFAP2A, which was demonstrated in a heatmap and a volcano plot." (PMID 38702698, 2024).
prostate tumor (6 papers, 2015 to 2023). "Our results demonstrated that IL-6 induction in prostate tumor spheres upregulates NANOG gene expression." (PMID 37987305, 2023). "Inducing IL-6 in prostate tumor spheres stimulates stemness biomarker NANOG genes." (PMID 37987305, 2023).
serous ovarian carcinoma (6 papers, 2013 to 2024). "NANOG is increased in expression from normal tissue, benign, borderline, and malignant tumors of ovarian serous cystadenocarcinomas and protein is found selectively associated with high-grade ovarian serous carcinoma." (PMID 29499737, 2018). "Using 3 mL of conditioned media from each cell line, we confirm that CA11 mRNA is 0.1–0.5-fold lower abundance and NANOG is 50-fold higher abundance in EVs released from high-grade serous ovarian cancer cells, OVCA3." (PMID 29499737, 2018). "Among epithelial cells of the OSE in women with serous ovarian carcinoma, we observed a population of small NANOG-positive cells with diameters of up to 5 μm and nuclei that filled up almost the entire cell volumes, a characteristic of stem cells." (PMID 28231820, 2017). "Similar populations of SOX2 and SSEA-4-positive cells were found in ovarian sections of women with high-grade serous ovarian carcinoma and their expression nicely matched with NANOG expression." (PMID 26940129, 2016). "On the other hand, it was clearly visible that some of tumor-like structures were composed of small cells, which were NANOG-positive, especially in the ovarian tissue of women with serous ovarian carcinoma." (PMID 26940129, 2016). "Moreover, CSCs expressing vimentin, NANOG and other markers of pluripotency were found in tumor tissue sections of women with high grade serous ovarian carcinoma." (PMID 32679765, 2020). "Other than in “healthy” ovaries, similar small, NANOG-positive cells were present in special “chambers” of unknown origin in the ovaries of women with borderline ovarian cancer or high-grade serous ovarian carcinoma." (PMID 26940129, 2016). "As expected, small round cells were observed in ovarian surface epithelium after HE staining and some of them also expressed NANOG-positivity (brown staining) in both ovarian tissue sections of women with borderline ovarian cancer and high-grade serous ovarian carcinoma." (PMID 26940129, 2016).
acute myeloid leukemia (5 papers, 2017 to 2022). Acute myeloid leukemia (AML) is a group of neoplasms arising from precursor cells committed to the myeloid cell-line differentiation. "For example, NKL homeobox gene NANOG is normally expressed only in early stages of hematopoiesis and aberrantly activated in acute myeloid leukemia (AML) patients." (PMID 34072771, 2021). "Besides, overexpression of FTO in acute myeloid leukemia cells could decrease m6A modification of NANOG and SOX2 and increase their mRNA levels, which was consistent with our studies in HCC cells." (PMID 33783988, 2021).
basal cell carcinoma (5 papers, 2012 to 2023). A carcinoma involving the basal cells.
brain tumors (5 papers, 2016 to 2022). "Transcriptomic analyses showed that OCT4A, NANOG, and SOX2 were overexpressed in brain tumors." (PMID 35565225, 2022).
dysplasia (5 papers, 2019 to 2025). A usually neoplastic transformation of the cell, associated with altered architectural tissue patterns. "In our study, NANOG expression was noticed in 71.4% of dysplasia cases, and all these samples showed cytoplasmic staining of cells." (PMID 38558704, 2024). "NANOG can also be used as a biomarker to predict the progression of the disease from dysplasia to OSCC." (PMID 38558704, 2024). "Thirty-six cases of high-grade dysplasia (HG-dysplasia), 31 cases of low-grade dysplasia (LG-dysplasia), 15 cases of OSCC, 15 cases of LG-dysplasia adjacent to OSCC, and 15 cases of normal oral mucosa were analyzed for NANOG protein expression." (PMID 33643897, 2020). "We therefore analyzed expression of NANOG, NANOG-regulating miRNAs and lncRNAs in OSCC cancerogenesis, using oral biopsy samples from 66 patients including normal mucosa, dysplasia, and OSCC." (PMID 33643897, 2020).
laryngeal carcinoma (5 papers, 2014 to 2021). Carcinoma that arises from the laryngeal epithelium. "Strong NANOG expression was found in 22 (27%) lesions and was established as cut-off point, showing the most robust association with laryngeal cancer risk (p = 0.003) superior to the histological classification (p = 0.320)." (PMID 33058010, 2021). "In agreement with our results, NANOG expression was also revealed as a strong significant predictor of laryngeal cancer risk in patients with precancerous lesions, beyond histological grading." (PMID 31484317, 2019). "It is also worth noting that strong cytoplasmic NANOG expression showed the most robust association with laryngeal cancer risk and superior predictive power than the histological classification, which remains the current gold standard in the clinical practice." (PMID 28894270, 2017). "Nuclear NANOG expression also tended to associate with increased laryngeal cancer risk (Fisher’s exact test, P = 0.186)." (PMID 28894270, 2017). "Univariate Cox analysis showed that strong cytoplasmic NANOG expression was the only significant predictor of laryngeal cancer risk." (PMID 28894270, 2017). "More importantly, the results obtained in the validation cohort confirmed the relationship of NANOG expression with laryngeal cancer risk." (PMID 28894270, 2017). "In this study, NANOG protein expression was evaluated by immunohistochemistry using two independent cohorts of patients with LD and correlated with clinicopathological parameters and laryngeal cancer risk." (PMID 33058010, 2021). "Also in this cohort, univariate Cox analysis showed that strong cytoplasmic NANOG expression was the better predictor of laryngeal cancer risk." (PMID 28894270, 2017). "Interestingly, we found that cytoplasmic NANOG protein scores significantly correlated with an increased laryngeal cancer risk (log-rank P = 0.007)." (PMID 28894270, 2017). "NANOG protein expression was evaluated by immunohistochemistry using two large independent cohorts of patients with laryngeal precancerous lesions, and correlated with clinicopathological parameters and laryngeal cancer risk." (PMID 28894270, 2017). "Strong NANOG expression was found in 22 (27%) lesions and was established as cut-off point, showing the most robust association with laryngeal cancer risk (P = 0.003) superior to the histological classification (P = 0.320) the current gold standard in the clinical practice." (PMID 28894270, 2017). "Five years after the initial diagnosis, only 20% of patients with negative to moderate NANOG expression and 55% of patients with strong NANOG expression developed laryngeal cancer." (PMID 33643897, 2020). "NANOG is a master regulator of embryonic stem cell pluripotency, found to be frequently aberrantly expressed in a variety of cancers, including laryngeal carcinomas." (PMID 28894270, 2017). "Therefore, cytoplasmic NANOG expression emerges as a clinically and biologically relevant feature in early stages of laryngeal tumourigenesis that contributes to malignant transformation and laryngeal cancer development." (PMID 28894270, 2017). "At 5 years after the patients were diagnosed, 55% of the patients with strong cytoplasmic NANOG expression developed laryngeal cancer compared with 20% of the patients with negative to moderate NANOG expression (Fisher’s exact test, P = 0.005)." (PMID 28894270, 2017). "Patients carrying strong cytoplasmic NANOG-expressing lesions (score 2) experienced a significantly higher progression to laryngeal cancer than those with absent to moderate (scores 0–1) expression (HR = 1.826; 95%CI, 1.222–2.728; P = 0.003)." (PMID 28894270, 2017).
lymphoma (5 papers, 2016 to 2022). A malignant (clonal) proliferation of B- lymphocytes or T- lymphocytes which involves the lymph nodes, bone marrow and/or extranodal sites. "Second, we analyzed perturbation signatures of artificially induced overexpression of MYC in lymphomas of Eμ-Myc-transgenic mice as well as knock-out experiments of NANOG, POU5F1 and SOX2 in human embryonic stem cells." (PMID 29741575, 2018). "A small fraction of lymphoma cells that survived after drug application showed higher expression of stem cell markers (NANOG, andSOX2) and superior ability of self-renewal and sphere formation, compared to untreated control cells (P < 0.05)." (PMID 27911272, 2017). "Second, we analyzed perturbation signatures of (i) mouse lymphomas with artificially induced MYC overexpression and (ii) knock-out experiments of NANOG, POU5F1 and SOX2 in human embryonic stem cells." (PMID 29741575, 2018). "For instance, B-cell eCGIs are enriched for regions binding key TFs involved in B-lymphopoiesis and lymphoma pathogenesis (such as BCL11A, EBF1, IKZF1 and SPI1), whereas ESC-specific eCGIs are enriched for binding of NANOG, a key TF regulating pluripotency." (PMID 26512062, 2016). "Second, we analyzed perturbation signatures of (i) mouse lymphomas with artificially induced overexpression of MYC and (ii) knock-out experiments of NANOG, POU5F1 and SOX2 in human embryonic stem cells to examine if the different methods are able to identify the perturbed regulators." (PMID 29741575, 2018).
teratocarcinoma (5 papers, 2006 to 2023). A germ cell tumor characterized by the presence of an embryonal carcinoma component and a teratoma component. "In human, the chromosome region where NANOG is located also contains DPPA3, POU5F1P3 and another pluripotency factor, GDF3, and collectively is called a ‘hotspot for teratocarcinoma’ owing to the high rate of chromosomal abnormalities." (PMID 36621005, 2023). "It has been clearly demonstrated that human stella-related (STELLAR), NANOG, and GDF3 genes are expressed in pluripotent cells and mapped to chromosome 12p13, which is a hotspot for teratocarcinoma." (PMID 37205315, 2023). "The chromosome region with adjacent localization of the genes NANOG, STELLAR, and GDF3 has been considered as a hotspot for teratocarcinoma." (PMID 16670017, 2006).
yolk sac tumours (5 papers, 2007 to 2026). "Expression of the stem cell-related markers OCT-3/4 and KIT were present in 80% of dysgerminomas, 75–100% of tumours containing gonadoblastoma and in two yolk sac tumours, whereas NANOG and AP-2γ were present in approximately half of the dysgerminomas and gonadoblastomas." (PMID 17274819, 2007).
neuroblastoma (4 papers, 2019 to 2023). Neuroblastoma (NB) is the most common solid, extracranial childhood tumor. "The pluripotency-maintaining transcription factor NANOG maintains a high self-renewal capacity of embryonic stem cells and is a CSC-like marker associated with poor prognosis in neuroblastoma." (PMID 36980635, 2023). "Most importantly, R+D ‘pre-treatment’ compared to control (vehicle) treatment proficiently reduced the elevated CXCR4, BMI1 and NANOG protein expression in spheroid cultures in both neuroblastoma cell lines." (PMID 36980635, 2023). "SK-N-BE neuroblastoma cells were shown to form CD133+ tumorspheres, unlike SH-SY5Y cells, hence we have first sorted CD133− and CD133+ SK-N-BE cells and showed that expression of CD133, ELK-1, SOX2, NANOG, and POU5F1 were all significantly more in CD133+ cells than in CD133− cells." (PMID 33672811, 2021).
Obesity (4 papers, 2020 to 2023). Accumulation of substantial excess body fat. "High AMD1 level could promote SRY‐box transcription factor 2 (SOX2), Kruppel like factor 4 (KLF4), and NANOG expression of HCC cells through obesity–associated protein (FTO)‐mediated mRNA demethylation." (PMID 33783988, 2021). "CUX1, NANOG, GATA4 and HIF1A plays a vital role in the patients with obesity." (PMID 36837510, 2023).
skin cancer (4 papers, 2015 to 2023). "Taken together, our data reveal that NANOG regulates TH metabolism and that the NANOG-dependent D2 expression is a pivotal transcriptional network exacerbating the expression of invasiveness genes in skin cancer." (PMID 32197405, 2020). "In summary, we described a hitherto unknown function of the NANOG protein, namely, that it induces TH signaling activation in skin tumors." (PMID 32197405, 2020). "To address whether high levels of NANOG can contribute to tumorigenesis, we induced skin tumors using the classical two-stage chemical carcinogenesis protocol based on the mutagen 7,12-dimethylbenz(a)anthracene (DMBA) and the promoter TPA21." (PMID 25988972, 2015). "Consistently, the expression of Slug was positively correlated with the expression of CSC markers such as CD44, NANOG, ALDH1A1 and KLF4 in skin cancer." (PMID 27901498, 2017). "An Oncomine database analysis also demonstrated that VEGF-C expression was positively correlated with the expression of some CSC markers, such as OCT4, KLF4, NANOG, CD44, CD34 and CD133, suggesting that VEGF-C increases the CSC features of skin cancer cells." (PMID 27901498, 2017). "Therefore, we examined whether VEGF-C affects cancer stemness in skin cancer cells and found that knockdown of VEGF-C significantly decreased the expression of the CSC markers SOX2, OCT4, KLF4, NANOG, CD133, CD34 and CD44 as well as ALDH activity, which is a hallmark of CSCs." (PMID 27901498, 2017).
astrocytomas (3 papers, 2013 to 2021). "We attempted to identify HIF-1α-regulated quiescent stem-like tumor cells in astrocytoma tissues using the following immunophenotypes as indices: SOX2+ HIF-1α+ RNApII-S2P-/low or NANOG+ HIF-1α+ RNApII-S2P-/low." (PMID 26799577, 2016). "NANOG levels did not correlate to any of the other analyzed targets, and its expression pattern in GBM cases was random, enabling us to speculate that NANOG works differently to contribute to astrocytoma formation." (PMID 23613880, 2013).
cervical intraepithelial neoplasia (3 papers, 2017 to 2025). "The aim of the present study was to assess a diagnostic potential of stem cell markers NANOG and SOX2 for classifying cervical squamous intraepithelial lesions (SILs)/cervical intraepithelial neoplasia (CIN)." (PMID 40272007, 2025).
colorectal tumor (3 papers, 2017 to 2020). "NANOG was related to multiple colorectal tumor development functions, including liver metastasis, stemness maintaining and prognosis." (PMID 29228695, 2017). "Studies showed that normal colon mucosa has low or undetectable NANOG and NANOGP8, whereas colorectal tumor tissues and cancer cells have elevated NANOGP8 expression with no changes in NANOG." (PMID 28453235, 2017).